RGS3 (regulator of G protein signaling 3)
Description:
Down-regulates signaling from heterotrimeric G proteins by increasing the GTPase activity of the alpha subunits, thereby driving them into their inactive GDP-bound form. Down-regulates G protein-mediated release of inositol phosphates and activation of MAP kinases.
Synonyms: RGP3; C2PA; FLJ20370; PDZ-RGS3
Tractability: Small molecule: it has a binding pocket of medium quality. Antibody: UniProt places it where antibodies can reach, with high confidence; its Gene Ontology location is reachable by antibodies, with high confidence; the Human Protein Atlas places it where antibodies can reach. PROTAC: UniProt records ubiquitination sites on it; ubiquitination databases record sites on it; its protein half-life has been measured.
Gene: Protein-coding gene on chromosome 9 (113,444,731 to 113,597,743, forward strand). Ensembl gene ENSG00000138835.
Subcellular location: Cytoplasm; Nucleus; Cell membrane
Subcellular location (Human Protein Atlas): Plasma membrane
Pathways (Reactome):
Signal Transduction: G alpha (i) signalling events; G alpha (q) signalling events
Gene Ontology:
Molecular function: protein binding; GTPase activator activity; GTPase activity
Biological process: G protein-coupled receptor signaling pathway; regulation of G protein-coupled receptor signaling pathway
Cellular component: cytoplasm; nucleus; plasma membrane; cytosol
Genetic constraint (gnomAD): Loss-of-function variants: 63 observed, 116.73 expected, observed/expected ratio (o/e) 0.54, 90% interval 0.44 to 0.67. The upper end of that interval is the gene's LOEUF score, 0.67, which puts it in group 2 of 6, group 1 being the genes least tolerant of losing a copy. Missense variants: 1,319 observed, 1,485.6 expected, observed/expected ratio (o/e) 0.89, 90% interval 0.85 to 0.93. Synonymous variants: 570 observed, 610.78 expected, observed/expected ratio (o/e) 0.93, 90% interval 0.87 to 1.
Homologues: Orthologues: chimpanzee RGS3 (98% identical), macaque RGS3 (98% identical), rat Rgs3 (82% identical), rabbit RGS3 (82% identical), dog RGS3 (75% identical), guinea pig RGS3 (71% identical), mouse Rgs3 (70% identical), zebrafish si:ch211-154e10.1 (16% identical), zebrafish rgs3a (12% identical). Paralogues in human: RGS12 (13% identical), RGS22 (9% identical), RGS6 (9% identical), RGS4 (9% identical), RGS7 (9% identical), RGS11 (9% identical), RGS5 (9% identical), RGS16 (9% identical), RGS9 (8% identical), RGS8 (8% identical), RGS1 (8% identical), RGSL1 (8% identical), and 11 more.
Diseases named in the same sentence as RGS3 in open-access papers:
RGS3 is named in the same sentence as 28 diseases in open-access papers, as found by Europe PMC text mining. Sharing a sentence is not in itself a finding about the gene and the disease. The quoted sentences say what the papers report.
gastric cancer (9 papers, 2019 to 2025). A primary or metastatic malignant neoplasm involving the stomach. "High expression of RGS1, RGS2 and RGS3 in patients with gastric cancer has been shown to be associated with poor prognosis or poor tumor stage." (PMID 38693916, 2024). "Higher expression of RGS3 was associated with a larger tumor size, lymph node metastasis, and local invasion in gastric cancer." (PMID 35795065, 2022). "High expression of RGS1 and RGS3 is associated with poor prognosis in patients with gastric cancer." (PMID 38693916, 2024). "RGS3 is a GTPase-activating protein that inhibits G-protein-mediated signal transduction and associated with tumor cell proliferation and migration in glioma and gastric cancer." (PMID 35111672, 2021). "Similar phenomena can be observed in gastric cancer, where the expression levels of RGS3 is apparently increased and overexpression of RGS3 markedly promotes gastric cancer cell proliferation." (PMID 37118788, 2023). "For example, RGS3 is highly expressed in gastric cancer and efficiently promotes tumor growth, and is correlated with poor prognosis." (PMID 36214767, 2022). "In gastric cancer, RGS3 has been reported overexpressed in tumor cells and played a critical role in the Wnt signaling pathway on epithelial-mesenchymal transition." (PMID 36214767, 2022). "It has been reported that miR-133a regulates RGS3 in gastric cancer, and the miR-133a-RGS3 axis may be involved in the malignant progression of the disease." (PMID 39901299, 2025). "RGS3 does not appear to be associated with prognosis in patients with gastric cancer, whereas RGS5, which has been shown to be associated with abnormal vascular formation, is a prognostic risk factor in three gastric cancer cohorts." (PMID 38693916, 2024). "In addition, microRNA-133a is also negatively correlated with RGS3 levels in gastric cancer, with significantly higher expression of RGS3 in gastric cancer cells and tissues than in corresponding normal tissues and cells." (PMID 37924113, 2023). "The overexpressed RGS3 in the tissues of patients with gastric cancer could lead to a poor prognosis, which could be negatively regulated by miR-126." (PMID 31632984, 2019).
glioma (6 papers, 2011 to 2025). A benign or malignant brain and spinal cord tumor that arises from glial cells (astrocytes, oligodendrocytes, ependymal cells). "An additional SNP of interest is rs12341266 at 9q32, which has an FDR of 0.06 and is in the glioma associated gene, RGS3." (PMID 21827660, 2011). "In addition, RGS3 has been reported to modulate glioma cell mobility." (PMID 21698121, 2011). "RGS3 and RGS4, which share a similar function with RGS11 in modulating Gαi/o activity are overexpressed in faster migrating glioma cells, which results in greater cell adhesion and chemotaxis." (PMID 27105500, 2016). "Overexpression of RGS3 and RGS4 leads to the blockade of Gα-dependent chemotaxis in lymphoid cells, whereas increasing expression of either of these RGS proteins increases cell adhesion and chemotaxis in glioma cells." (PMID 27105500, 2016).
lung carcinoma (5 papers, 2011 to 2023). "Previously, it was reported that overexpression of microRNA-25 influenced the expression of RGS3 leading to the inhibition of apoptosis of lung cancer cells." (PMID 37462692, 2023). "And recently, RGS3 was reported to hinder the effect of KRASG12C inhibitors in the targeted therapy of lung cancer by enhancing the GTPase activity of KRAS." (PMID 36214767, 2022). "miR-25 was reported to inhibit apoptosis in lung cancer by targeting RGS3 and MOAP1." (PMID 30992737, 2019). "We further identified RGS3 as a target gene of miR-92a in lung cancer." (PMID 31632984, 2019).
breast carcinoma (4 papers, 2011 to 2024). "HMGB3, XRCC4, RGS3 and PFKL have been identified as potential target genes for breast cancer in many studies, providing more directions for the treatment of breast cancer patients." (PMID 39669558, 2024). "As expected, seven of the TME prognostic genes (NOS2, SCG2, RGS3, EMP1, PDLIM4, PCDH9, and GFI1) showed dual functions in breast cancer progression." (PMID 36936167, 2023). "Seven of the 15 TME prognostic genes (NOS2, SCG2, RGS3, EMP1, PDLIM4, PCDH9, and GFI1) were involved in enhancing cell proliferation, destroying cell apoptosis, promoting cell invasion, or migration in breast cancer." (PMID 36936167, 2023).
cardiac hypertrophy (2 papers, 2017 to 2023). "Additionally, RGS3 is known to protect against cardiac hypertrophy by blocking the MEK/ERK signaling pathway." (PMID 28724429, 2017). "Thus, cardiac RGS3 may play important roles in the modulation of cardiac hypertrophy and HF progression, as well as in the regulation of cardiac function in general." (PMID 37047106, 2023).
ovarian carcinoma (2 papers, 2024 to 2025). A malignant neoplasm originating from the surface ovarian epithelium. "This five-gene signature (RGS11, RGS10, RGS13, RGS4, and RGS3) is overexpressed in ovarian cancer and involved in extracellular matrix–receptor interaction, the TGF-β signaling pathway, the Wnt signaling pathway, and the chemokine signaling pathway." (PMID 39145770, 2024).
Arrhythmia (1 paper, 2025). Any cardiac rhythm other than the normal sinus rhythm. "The results show that miR-126-3p can suppress RGS3 expression by targeting the RGS3 gene, providing mechanistic insight into the role of miR-126-3p in modulating cardiac ion channel function and suggesting potential therapeutic targets for arrhythmia management." (PMID 39901299, 2025).
asthma (1 paper, 2018). "For example, lack of Gq-inhibitory protein RGS3 in mice reveals exacerbated inflammation in a mouse model of asthma." (PMID 29621314, 2018).
astrocytoma (1 paper, 2015). "The order of potency of adenosine agonists in the down-regulation of RGS3 expression in astrocytoma cells is NECA>CPA/IB-MECA> CGS21680 indicating that the effect is due to activation of A2B-receptors." (PMID 26263491, 2015). "Incubation with the non-selective adenosine receptor agonist NECA leads to up-regulation of expression of RGS2 mRNA and down-regulation of RGS3 in astrocytes, similar to its effects in astrocytoma cells." (PMID 26263491, 2015). "Expression of RGS-3 was inhibited by adenosine agonists in both astrocytoma cells and astrocytes." (PMID 26263491, 2015). "Incubation with the non-selective adenosine receptor agonist NECA leads to up-regulation of expression of RGS2 mRNA and down-regulation of RGS3 and RGS4 in U373 astrocytoma cells." (PMID 26263491, 2015). "The present work shows that in U373 astrocytoma cells adenosine agonists up-regulate RGS2 mRNA expression and down-regulate expression of RGS3 and RGS4." (PMID 26263491, 2015).
atherosclerosis (1 paper, 2018). A disease characterized by the build-up of fatty material and calcium deposition in the arterial wall resulting in partial or complete occlusion of the arterial lumen. "By searching miRs target gene predicting database and available published reference, we found 17 potential miR-92a target genes related to vascular inflammation and atherosclerosis and only 3 with anti-atherogenic properties, which are RGS3, KLF2 and GDF11." (PMID 29777114, 2018).
ciliopathies (1 paper, 2009). "However, nuclear GFP::EGL-4 in naïve tax-2/4 mutant animals was correlated with ciliopathies in the same way that was observed for rgs-3." (PMID 20011101, 2009).
glioblastoma (1 paper, 2015). The most malignant astrocytic tumor (WHO grade IV). "Indeed, it was found that in U373MG as well as primary glioblastoma cells both adhesion and migration, possible promotors of malignancy, were enhanced in clones exhibiting an increased expression of RGS3 and -4." (PMID 26263491, 2015).
liver cancer (1 paper, 2022). An epithelial or non-epithelial malignant neoplasm that arises from the liver. "To date, 20 canonical RGS genes (RGS1-RGS20) have been reported and a few members of the RGS family (RGS3, RGS5, RGS17) have also been associated with liver cancer." (PMID 36009801, 2022).
multiple sclerosis (1 paper, 2013). A progressive autoimmune disorder affecting the central nervous system resulting in demyelination. "Exceptional PD-related examples of seemingly active miRNA-spliced transcripts predicted interactions include USP13, which promotes smooth (SMO) signaling by preventing its ubiquitination, RGS3 which contributes to neural progenitor/stem cell regulation and MGAT1, involved in multiple sclerosis." (PMID 23717260, 2013).
ovarian serous carcinoma (1 paper, 2025). "Our bioinformatics analysis revealed significant overexpression of RGS3 in OC tissues, further corroborated by IHC showing elevated RGS3 expression in ovarian serous carcinoma and lymphatic metastases." (PMID 40456746, 2025). "Analysis from the GEPIA database analysis revealed that RGS3 is upregulated in multiple tumor types, with notably higher mRNA levels in ovarian serous carcinoma compared to normal ovarian surface epithelium." (PMID 40456746, 2025).
type 2 diabetes mellitus (1 paper, 2021). A type of diabetes mellitus that is characterized by insulin resistance or desensitization and increased blood glucose levels. "Genes such as KCNE2, DLL1, ACVR1C, RGS3, MLXIPL (MLX interacting protein like), PAG1, SLC2A10 and GRB14 play important role in type 2 diabetes mellitus progression." (PMID 33902539, 2021).
tumor (14 papers, 2015 to 2025). "Also, in TNBC overexpression of mir-126 inhibited proliferation, metastasis and angiogenesis by targeting the regulator of G-protein signaling (RGS3), a gene that is associated with tumour progression and metastasis." (PMID 34179081, 2021). "In a Nod-SCID mouse xenograft model, at the end of the study, RGS3 knockdown significantly slowed tumor growth and reduced tumor size compared to the control group, while RGS3 overexpression accelerated tumor growth and increased tumor size." (PMID 40456746, 2025). "Herein, this research elucidated that the overexpression of RGS3 in OC correlates with adverse clinical pathological features and tumor progression." (PMID 40456746, 2025). "In contrast, RGS3-knockdown cells formed fewer metastatic lesions, with a significant reduction in tumor weight." (PMID 40456746, 2025). "To evaluate the effect of RGS3 on tumor growth in vivo, we infected SKOV3 and OVCAR8 cells with lentiviruses expressing either shRGS3 or control constructs." (PMID 40456746, 2025). "Further proliferation, migration, and invasion assays also confirmed that silencing ARID3B effectively reversed the promotion of tumor cell proliferation and metastatic potential by RGS3 overexpression." (PMID 40456746, 2025). "In OC, the proliferation and migration phenotypes are particularly critical for tumor metastasis, yet RGS3’s role remains underexplored." (PMID 40456746, 2025). "Accumulating evidence has indicated the pivotal function of RGS3 in participating in the Wnt signaling and the epithelial-mesenchymal transition, which strongly suggested RGS3 as a tumor enhancer." (PMID 36214767, 2022). "The high expression characteristic of RGS3 in GC cells is consistent with the observation through IHC of tumor tissues." (PMID 28977866, 2017). "Reciprocally, other targets like RGS3 are generally upregulated in OAC but show higher levels in tumours with local metastases." (PMID 25889361, 2015). "Taken together, our results indicate an inhibitory effect of RGS3 knockdown on tumor development and suggest that targeting RGS3 could be a novel therapeutic strategy for treating OC." (PMID 40456746, 2025). "Emerging oncological evidence suggests that RGS3 may contribute to the progression of tumor metastasis of various cancers, including gastric, liver, and lung cancers." (PMID 40456746, 2025). "Furthermore, we demonstrated that silencing RGS3 promotes apoptosis, effectively inhibiting tumor growth and metastasis." (PMID 40456746, 2025). "Three genes (RARS, MC1R, and RGS3) were involved in tumor metastasis other than CRC." (PMID 35795065, 2022). "The modulation of either miR-145-5p or RGS3 for rescue experiments could significantly recover the phenotypes of tumor cell growth and maintenance induced by UBE2MP1." (PMID 36214767, 2022). "miR126-3p serves as a tumor suppressor via controlling RGS3, an essential regulator of TNBC." (PMID 34778378, 2021). "The luciferase assay demonstrated that miR-92a could directly bind to the 3′-UTR to decrease the expression of RGS3, one of the “cancer signature” genes owing to its vital role in tumor development." (PMID 31632984, 2019). "IHC analysis of the tumor tissues revealed decreased expression of CD31, Vimentin, and N-Cadherin in RGS3-knockdown tumors." (PMID 40456746, 2025). "Among the tumor specimens, 78.26% (18/23) of the cases presented high level ROBO1, and only 21.74% (4/17) cases showed relatively lower RGS3 expression." (PMID 28977866, 2017). "We concluded and illustrated the tumor-promoting mechanism of UBE2MP1, independent of its parental genes, by modulating the miR-145-5p/RGS3 axis." (PMID 36214767, 2022).
cancer (7 papers, 2015 to 2025). A tumor composed of atypical neoplastic, often pleomorphic cells that invade other tissues. "In addition, RGS3, a G-protein signaling inhibitor, has been implicated in cell proliferation and apoptosis in cancer." (PMID 31494269, 2019). "Collectively, these findings suggest that RGS3 is involved in the apoptosis of OC cells, underscoring its potential significance in cancer biology." (PMID 40456746, 2025). "This reveals a novel aspect of RGS3’s role in cancer biology, offering potential new avenues for therapeutic intervention." (PMID 40456746, 2025). "Briefly, RGS3 enhances the invasive and stem cell properties of cancer cells and interacts with noncoding small RNAs, which are important for the development of tumour cells." (PMID 37924113, 2023). "For example, miR-25 is negatively correlated with RGS3 expression, and its interaction is involved in the regulation of cancer cell stemness in non-small cell lung cancer." (PMID 37924113, 2023). "For example, UHRF1 and RGS3 are both overexpressed in general in cancers but they showed evidence of increased expression in late stage disease (significantly enhanced in patients with distant and local metastases respectively)." (PMID 25889361, 2015). "RGS3 inhibits the activity of miR-126-3p and neutralizes the antiproliferative effects of TGF-β in cancer cells." (PMID 39409003, 2024). "Among the top 10 DRGs identified for Korean (GSE24375), six genes are GC related (ESRRG, LIMS1, GATA3, GATA6, SOX9, POU2F1) and the other four are cancer related (IRF2, RGS3, MRPL36, FOSB)." (PMID 29745833, 2018).
mitochondrial disease (1 paper, 2025). "Furthermore, we observed signals in important genes associated with ASD pathways, such as RGS3 in Cluster 24, encoding a regulator of G protein signaling; NUBPL in Cluster 25, previously associated with mitochondrial disease; and OR13F1 in Cluster 8, encoding an olfactory receptor." (PMID 40440618, 2025).
RGS3 also shares sentences with these, for which no sentence is quoted: Anxiety (1 paper); craniosynostosis (1); heart failure (1); hepatocellular carcinoma (1); heroin addicts (1); lymph node metastasis (1); soft tissue sarcoma (1); Takotsubo cardiomyopathy (1); triple-negative breast carcinoma (1).